KAZN (kazrin, periplakin interacting protein)
Description:
Component of the cornified envelope of keratinocytes. May be involved in the interplay between adherens junctions and desmosomes. The function in the nucleus is not known.
Synonyms: C1orf196; KAZ; KIAA1026; KAZRIN; FLJ43806
Tractability: Antibody: its Gene Ontology location is reachable by antibodies, with high confidence. PROTAC: its protein half-life has been measured.
Gene: Protein-coding gene on chromosome 1 (13,892,792 to 15,118,043, forward strand). Ensembl gene ENSG00000189337.
Subcellular location: Cytoplasm, cytoskeleton; Cytoplasm (Isoform 2); Cell junction, desmosome; Nucleus; Cytoplasm (Isoform 3); Cytoplasm (Isoform 4)
Subcellular location (Human Protein Atlas): Nucleoplasm; Cytosol; Nuclear speckles
Pathways (Reactome):
Developmental Biology: Formation of the cornified envelope
Gene Ontology:
Molecular function: protein binding
Cellular component: cornified envelope; cytosol; desmosome; nuclear speck; nucleoplasm; cytoplasm; cytoskeleton; nucleus
Genetic constraint (gnomAD): Loss-of-function variants: 40 observed, 75.86 expected, observed/expected ratio (o/e) 0.53, 90% interval 0.41 to 0.69. The upper end of that interval is the gene's LOEUF score, 0.69, which puts it in group 2 of 6, group 1 being the genes least tolerant of losing a copy. Missense variants: 897 observed, 1,008.7 expected, observed/expected ratio (o/e) 0.89, 90% interval 0.84 to 0.94. Synonymous variants: 464 observed, 426.5 expected, observed/expected ratio (o/e) 1.09, 90% interval 1.01 to 1.17.
Homologues: Orthologues: chimpanzee KAZN (100% identical), macaque KAZN (99% identical), dog KAZN (96% identical), rat Kazn (95% identical), mouse Kazn (94% identical), zebrafish kazna (62% identical), pig KAZN (58% identical), tropical clawed frog kazn (44% identical), guinea pig Kazn (43% identical), zebrafish kaznb (40% identical), Drosophila melanogaster Liprin-gamma (35% identical).
Diseases named in the same sentence as KAZN in open-access papers:
KAZN is named in the same sentence as 23 diseases in open-access papers, as found by Europe PMC text mining. Sharing a sentence is not in itself a finding about the gene and the disease. The quoted sentences say what the papers report.
schizophrenia (3 papers, 2019 to 2024). A major psychotic disorder characterized by abnormalities in the perception or expression of reality. "The KAZN gene is associated with PTSD and schizophrenia, as well as three neurodegenerative diseases including Alzheimer’s disease, Parkinson’s disease, and amyotrophic lateral sclerosis." (PMID 34916497, 2021).
ovarian epithelial tumor (2 papers, 2022 to 2023). A benign, borderline, or malignant tumor that originates from the surface epithelium of the ovary. "Studies have also shown that KAZN was up-regulated in ovarian epithelial tumors and the expression of KAZN was correlated with the patients’ survival time." (PMID 37296706, 2023). "KAZN was up-regulated in ovarian epithelial tumors and the expression of KAZN was correlated with the patients’ survival time." (PMID 35710397, 2022).
psoriasis (2 papers, 2021 to 2023). An autoimmune condition characterized by red, well-delineated plaques with silvery scales that are usually on the extensor surfaces and scalp. "When comparing psoriasis-involved skin to the adjacent normal skin of patients with psoriasis, differentially methylated CpGs are found, some of which situated at the promoters of known PSORS genes, such as S100A9, PTPN22, SELENBP1, CARD14, and KAZN." (PMID 37628670, 2023).
Cirrhosis (1 paper, 2024). A chronic disorder of the liver in which liver tissue becomes scarred and is partially replaced by regenerative nodules and fibrotic tissue resulting in loss of liver function. "Changes in the methylation and transcriptional levels of ZBTB38, ZC3H3, FOXK1, and KAZN are important for the development of fibrosis and HCC; and are therefore potential therapeutic targets and diagnostic tools for cirrhosis and HCC." (PMID 38302914, 2024). "Notably, the methylation levels of KAZN were decreased in both cirrhosis and HCC and so were its expression levels as the liver progressed from cirrhosis, dysplastic nodules, and early HCC to advanced HCC." (PMID 38302914, 2024). "The decreased expression of KAZN could inhibit differentiation and stimulate the proliferation of liver cells in cirrhosis, leading to the development of HCC." (PMID 38302914, 2024).
gestational hypertension (1 paper, 2020). "The most notable gene common to GWAS Catalog and UKB datasets is the KAZN gene that is associated with 3 out of 4 traits in the UKB data: gestational hypertension, APH, and the delivery complicated by umbilical cord complications." (PMID 32403311, 2020).
Infertility (1 paper, 2023). "According to the literature, variants within the KAZN gene have also been associated with infertility and pregnancy- and labour-related complications." (PMID 37626618, 2023). "Moreover, the KAZN gene, which encodes a desmosomal protein involved in cell adhesion, cytoskeleton organisation, and embryonic tissue morphogenesis, has also been linked with EM and EM-related infertility." (PMID 37626618, 2023).
liver fibrosis (1 paper, 2024). "Changes in methylation and transcriptional levels of KAZN could alter the cytoskeleton in liver cells, resulting in the development of liver fibrosis and, consequently, HCC." (PMID 38302914, 2024).
ovarian carcinoma (1 paper, 2022). A malignant neoplasm originating from the surface ovarian epithelium. "Our results indicated that the expression and methylation patterns of KAZN were closely associated with the oncogenesis of ovarian cancer." (PMID 35710397, 2022). "The dataset from CPTAC Ovarian Cancer Confirmatory Study contains 41 normal participants and 169 tumor participants, which was used to validate the KAZN protein expression in Ovarian cancer." (PMID 35710397, 2022). "KAZN mRNA was significantly up-regulated in OC in 10 GEO datasets, including 9 serous ovarian cancers and one unspecified ovarian cancer." (PMID 35710397, 2022). "Given the apparent heterogeneity (p = 0.01, I2 = 56%), a random-effects model was applied, and remarkable up-regulation (SMD = 1.18, 95% CI: 0.76, 1.61) of KAZN mRNA was found in ovarian cancer group." (PMID 35710397, 2022). "The results showed that KAZN expression was significantly upregulated in ovarian cancer tissue compared with normal control (p = 0.0087), which is." (PMID 35710397, 2022). "One of the merit of this work is the use of multiple data sources, which all indicated that KAZN was differentially expressed both on the mRNA level and on the protein level between ovarian cancer and normal tissues, with KAZN mRNA expression negatively correlated with survival time of the patients." (PMID 35710397, 2022). "The expression data of KAZN in ovarian cancer were obtained through the GEO database." (PMID 35710397, 2022). "The differentially expressed CpG sites, including 5 hypermethylated and 4 hypomethylated CpG sites in OC samples, may affect KAZN expression in different ways, whereby participating in the formation and progression of ovarian cancer." (PMID 35710397, 2022). "Therefore, according to the dynamic changes of KAZN expression during cell development and the regulation of gene expression by epigenetics in time and space, we postulate that the expression and methylation of KAZN are crucial in the occurrence and development of ovarian cancer." (PMID 35710397, 2022). "Survival analysis of cg17657618 showed a trend of longer survival time for the low CpG beta value group, though not statistically significant (p = 0.089), suggesting that KAZN methylation may have an important role in the development and outcome of ovarian cancer." (PMID 35710397, 2022). "To further study the clinical effects of KAZN in ovarian cancer, we divided the cases from TCGA OC datasets into four groups by the quantiles of KAZN counts, use quantile 1 and 4 as the KAZN high expression group and KAZN low expression group, and analyzed the survival status between the two groups." (PMID 35710397, 2022). "Hence, with continuous discovery of various global and specific DNMT inhibitors, CpG methylation sites of KAZN could be a new potential therapeutic target for ovarian cancer treatment." (PMID 35710397, 2022).
tumor (4 papers, 2018 to 2026). "This study also presents a new method to classify tumor and normal tissue in OC using DNA methylation pattern in the KAZN gene body region." (PMID 35710397, 2022). "We used qRT-PCR to detect the expression levels of the KAZN in 14 human samples (8 normal ovarian tissues and 6 tumor tissues)." (PMID 35710397, 2022). "We used data from Gene Expression Omnibus (GEO) microarrays, The Cancer Genome Atlas (TCGA), and Clinical Proteomic Tumor Analysis Consortium (CPTAC) to investigate the correlations between KAZN expression and clinical characteristics of OC by comparing methylation levels of normal and OC samples." (PMID 35710397, 2022). "The result showed that in the tumor group, the KAZN protein expression was significantly higher than in the normal group (p = 0.0027)." (PMID 35710397, 2022).
cancer (2 papers, 2022). A tumor composed of atypical neoplastic, often pleomorphic cells that invade other tissues. "Further understanding of the function of the KAZN gene and the mechanistic relationship between KAZN expression and methylation in cancer will open a new horizon for the control of malignant diseases." (PMID 35710397, 2022). "Recurrent KAZN variants have not been specifically associated with human tumors (COSMIC, Catalogue of Somatic Mutation in Cancer)." (PMID 34859285, 2022).
hematological malignancies (1 paper, 2022). "To date, PTBP2, TMEM51, and MTOR have been found as fusion partners of KAZN by RNA sequencing studies in solid tumors, while, as far as we know, rearrangements of KAZN have never been described in hematological malignancies." (PMID 34859285, 2022).
KAZN also shares sentences with these, for which no sentence is quoted: Parkinson (2 papers); alcoholism (1); Alzheimer disease (1); amyotrophic lateral sclerosis (1); autoimmune disease (1); breast tumors (1); diabetes (1); infection (1); liver disease (1); multiple sclerosis (1); neurodegenerative disease (1); serous ovarian cancers (1).